EGFR (epidermal growth factor receptor)
Diseases named in the same sentence as EGFR in open-access papers (continued):
Sharing a sentence is not in itself a finding about the gene and the disease.
intestinal cancer (11 papers, 2013 to 2025). "In particular, exposure to dietary components such as high fat diet has been associated with the modulation of experimental intestinal cancers via an EGFR-mediated mechanism." (PMID 32461676, 2020). "EGFR signaling pathway activation is another key process in the development and progression of many tumors, including intestinal cancer." (PMID 24279644, 2013). "Both transtuzumab and pertuzumab are included in this product for their capacity to actively target domains IV and II of the epidermal growth factor receptors (EGFR) respectively, that are overexpressed in several cancers like breast, cervical and intestinal cancers." (PMID 35808648, 2022). "The results of gastrointestinal tumor biomarker network analysis show that EGFR (epidermal growth factor receptor) is involved in regulating the proliferation and differentiation of trophoblast cells, and can be used as a predictive biomarker for intestinal cancers." (PMID 33692692, 2021). "Together, these data suggest there is crosstalk between WNT and EGFR signalling pathways in intestinal cancer and RAC1B mediated control of EGFR signalling activation is required for efficient WNT signalling activity." (PMID 33879799, 2021). "For patients with metastatic, EGFR antibody-resistant bowel cancers, a combination of trastuzumab and Lapatinib looks promising, but it is unclear whether the same combination is better than an EGFR antibody for patients who have never been treated for metastatic bowel cancer yet." (PMID 34885957, 2021).
leukopenia (11 papers, 2014 to 2025). "The main adverse events of almonertinib are elevation of CPK (19.6%), AST (12.3%), and ALT (11.4%), rash (12.7%), leukopenia (11.2%) and diarrhea (7.4%), which are superior to other EGFR-TKIs." (PMID 39334060, 2024). "Notably, AKT1, EGFR, IL6, STAT3, BCL2, CASP3, and JUN were identified as the top seven targets (degree >80) and may be key targets of QJSB in treating leukopenia." (PMID 39295929, 2024).
mesenchymal tumors (11 papers, 2012 to 2025). "In contrast, while small-scale exon 20 mutations of EGFR as detected in our 2 cases are common in epithelial tumors, e.g., non-small lung carcinoma, until recently, such alterations in mesenchymal tumors have been reported only in fibrous hamartoma of infancy." (PMID 39387892, 2024). "The basal-like 1 tumors have elevated expression of DNA damage response genes, while mesenchymal tumors were enriched for genes implicated in growth factor signaling pathways, including EGFR." (PMID 23071597, 2012). "Another group of MPNST-like cases included 5 low-grade mesenchymal neoplasms, of which 4 with TRK gene fusions (detected by either Archer VariantPlex or RNA-seq) and 1 with EGFR mutation (found by RNA-seq)." (PMID 38178234, 2024). "Of these, 26/27 genes were similarly upregulated in mesenchymal tumors versus all others with two genes also upregulated in the setting of EGFR amplification, likely reflecting the transcriptional and genomic features of the three EGFRvII-positive tumors." (PMID 24292886, 2014). "Thus, while ETV6::NTRK3 fusion identifies the homogeneous group of IF and the renal counterpart (cellular or mixed CMN), EGFR‐KDD mesenchymal neoplasms are a heterogeneous group of mesenchymal neoplasms which deserve further investigation." (PMID 40178433, 2025). "Similarly, EGFR‐KDDs have been detected in extra‐renal mesenchymal neoplasms with histologic features reminiscent of mixed CMN or IF/cellular CMN." (PMID 40178433, 2025). "In the second group, 5 morphologically and clinically low-grade mesenchymal neoplasms showed tyrosine kinase gene fusions/EGFR mutations and minimal or absent CNVs." (PMID 38178234, 2024). "Previous DNA and RNA-driven molecular subtyping predicts EGFR expression in the classical subset of glioblastoma tumors and CD44 expression in mesenchymal tumors." (PMID 32573435, 2020).
multiple sclerosis (11 papers, 2012 to 2023). A progressive autoimmune disorder affecting the central nervous system resulting in demyelination. "Increased EGFR expression in cell bodies of astrocytes during multiple sclerosis suggests their role in pathological plaques." (PMID 28792504, 2017).
papilloma (11 papers, 2013 to 2025). A benign epithelial neoplasm that projects above the surrounding epithelial surface and consists of villous or arborescent outgrowths of fibrovascular stroma. "Skin, papillomas, and cSCCs were obtained from Tpl2+/+ and Tpl2−/− mice and were stained for EGFR, p-EGFR, HER2, p-HER2, HER3 or p-HER3." (PMID 41154417, 2025). "Treatment with the EGFR inhibitor Gefitinib or EGFR/HER2 inhibitor Lapatinib resulted in a decrease in the number of papillomas by 88% and 50%, respectively, and restored the number of cSCCs back to Tpl2+/+ levels." (PMID 41154417, 2025). "Inhibition of p-MET by Capmatinib further increased expression of p-EGFR in v-rasHa-transduced Tpl2-/- keratinocytes and papillomas, supporting the notion of bypass pathway activation." (PMID 35325006, 2022). "Inhibition of MET by Capmatinib increased p-EGFR in Tpl2-/- keratinocytes and papillomas, and inhibition of EGFR by Gefitinib increased HER2 and HER3 signaling in both genotypes." (PMID 35325006, 2022). "In-vitro studies have shown that papilloma cells overexpress COX-2 as a result of enhanced Epidermal growth factor receptor (EGFR) signaling, and that this activity is important to their growth." (PMID 31620412, 2019). "Taken together, our results demonstrate that HPV8E6 alters the signaling of the UV-activated EGFR and this is a critical step in papilloma formation in response to UV-light in transgenic mice." (PMID 29176966, 2017). "EGFR inhibitors appear to improve papilloma disease control as an adjunct to surgical therapy—at least in some patients." (PMID 24795806, 2013). "Further, Tpl2 loss enhances p-EGFR, EGFR, and HER2 protein expression in papillomas." (PMID 41154417, 2025). "Additionally, immunohistochemical analysis of papillomas from Tpl2−/− mice showed upregulation in EGFR, p-EGFR and HER2." (PMID 41154417, 2025). "Tpl2−/− papillomas showed increased expression of EGFR, p-EGFR, and HER2 compared to Tpl2+/+ mice." (PMID 41154417, 2025). "IHC of EGFR in papillomas and invasive cancers in DBPDE treated mice was performed." (PMID 34784403, 2021). "We asked whether the activation of the RTK-activity of EGFR by HPV8E6 is relevant for the induction of papilloma growth in transgenic mice." (PMID 29176966, 2017). "Additionally, p-EGFR was strongly induced in papillomas from Capmatinib-fed mice compared to papillomas from wild type and Tpl2-/- mice on normal diet, and increased in SCCs compared to papillomas." (PMID 35325006, 2022). "Similarly, the HPV8E6-mediated transient boost of the RTK-activity of the EGFR may support papilloma growth." (PMID 29176966, 2017). "However, due to the EGFR expression in these patients’ papillomas it was hypothesized that EGFR antagonists could offer benefit." (PMID 24795806, 2013). "The superior efficacy of Gefitinib compared to Lapatinib suggests that EGFR signaling may be the predominant driver of tumorigenesis in this model, consistent with our observation that p-EGFR was the most strongly upregulated phospho-receptor in Tpl2−/− papillomas." (PMID 41154417, 2025). "and HER2-related microRNAs (miRs) 205 and 21 in keratinocytes, and enhances p-EGFR, EGFR, and HER2 protein expression in papillomas." (PMID 41154417, 2025). "Tpl2 ablation leads to increased gene expression of EGFR, HER2, and HER3 in Tpl2−/− keratinocytes and increased EGFR, p-EGFR, and HER2 protein levels in Tpl2−/− papillomas." (PMID 41154417, 2025). "These broader activities of HPV8E6 may support the progression of the benign papillomas, which depend on the RTK-activity of the EGFR as we have demonstrated here, to cSCC." (PMID 29176966, 2017). "p-EGFR expression in SCCs from Capmatinib-fed mice could not be assessed, as no papillomas in this group underwent malignant conversion to become SCCs." (PMID 35325006, 2022).
pemphigus (11 papers, 2018 to 2025). Pemphigus is a group of rare autoimmune diseases that cause blistering of the skin and mucous membranes (mouth, nose, throat, eyes, and genitals).This conditioncan occur at any age, but often strikes people in middle or older age. "Amongst the plethora of signaling events implicated in pemphigus pathogenesis, p38MAPK, EGFR, Src and PKC have been suggested to be central for regulation of desmosome turn-over." (PMID 31178865, 2019). "Moreover, several signaling pathways downstream of Ab binding, including p38 mitogen-activated protein kinase, EGFR, c-Myc, etc., have been shown to be involved in the loss of keratinocyte adhesion in pemphigus." (PMID 29535737, 2018). "Since in this context, Src families associated with EGFR activation were found to be activated by autoantibodies, our new data indicate that therapy options to enhance desmosome assembly may be effective to treat pemphigus in the future." (PMID 39882246, 2024). "One target molecule of Src in pemphigus pathogenesis appears to be EGFR which was shown to interact with and to be activated via Src." (PMID 34434944, 2021). "Dsg1-dependent suppression of EGFR/ERK signaling pathway has been shown to promote epidermal differentiation linking this signaling pathway to pemphigus autoantigens." (PMID 31867019, 2019). "EGFR downstream signalling is broad and the exact mechanisms involved in acantholysis are not perfectly clear but may involve PI3K and ERK which recently were associated with pemphigus pathogenesis." (PMID 34434944, 2021). "Furthermore, it was demonstrated to be involved in pemphigus signalling but not to be crucial because EGFR-independent loss of keratinocyte adhesion after incubation with PV-IgG has been observed as well." (PMID 34434944, 2021). "A similar role has been attributed to the epidermal growth factor receptor (EGFR); however, even accounting for recent advances, the role of apoptosis in pemphigus is still under investigation." (PMID 39201550, 2024). "Collectively, these data suggest that DSG3 inhibits YAP and promotes p‐YAP expression indirectly via inhibition of EGFR signalling and its downstream Hsp27 and c‐Jun in oral keratinocytes, the findings agreed with what has been characterised for DSG3 from pemphigus research." (PMID 35000271, 2022). "Based on the results presented here and elsewhere, EGFR, VEGFR2, and TrkA, as well as their downstream targets, seem to be more promising therapeutic targets for modulating intraepidermal blistering induced by pemphigus autoantibodies." (PMID 32815159, 2020). "The mechanism by which EGFR activation reduces desmosome adhesion in pemphigus is not fully understood." (PMID 31178865, 2019).
phyllodes tumor (11 papers, 2016 to 2025). A benign, borderline, or malignant fibroepithelial neoplasm arising from the breast and rarely the prostate gland. "Activating EGFR gene mutation was observed in one primary phyllodes tumor (presumed pathogenic V774 mutation)." (PMID 26625196, 2016). "In other study, EGFR over-expression was detected in 12.5% of benign, in 10% of borderline and 63% of all malignant phyllodes tumors." (PMID 38974258, 2023). "Overexpression of molecular biomarkers of increased angiogenesis, EGFR and immune checkpoints provides novel targeted therapy options in malignant phyllodes tumors of the breast." (PMID 26625196, 2016). "Using IHCs such as CK5/6, EGFR and p63 can aid in differentiating from phyllodes tumor." (PMID 36247506, 2022). "This comprehensive analysis elucidates the genomic landscape of phyllodes tumors, highlights molecular markers corresponding to histologic grade, broadens the range of tumors with frequent MED12 mutations, and identifies IGF1R and EGFR as potential therapeutic targets in malignant phyllodes tumors." (PMID 39996866, 2025). "Overexpression of EGFR and PDGFA is also present in malignant phyllodes tumors, which suggests the potential use of dual VEGFR/EGFR inhibitors (Vandetanib), a combination of anti-VEGFR and anti-EGFR and multikinase inhibitors (Panzopnib)." (PMID 37240386, 2023). "The presented results suggest that EGFR and CD10 overexpressed combined proteins in the phyllode tumor constitute, with histopathological parameters, an important prognostic factor." (PMID 38974258, 2023). "EGFR and CD10 overexpressed combined proteins in phyllode tumors constitute, with histopathological parameters, an important prognostic factor as well as a promising potential targets." (PMID 38974258, 2023). "However, still, the evaluation of EGFR as a potential biomarker in phyllodes tumors has not been well established, moreover, Tse12 suggested that the activation of EGFR mediated by EGF-family ligands is not the only mechanism by which proliferation occurs in phyllodes tumors." (PMID 38974258, 2023).
retinoblastoma (11 papers, 2012 to 2025). A malignant tumor that originates in the nuclear layer of the retina. "Further, lidocaine reduced the proliferation and induced the apoptosis of retinoblastoma cells by decreasing EGFR expression." (PMID 39888904, 2025). "Lidocaine inhibits proliferation and induces apoptosis in retinoblastoma cells by modulating the miR-520a-3p/EGFR axis." (PMID 35096852, 2021). "Suppression of miR-125a-5p upregulates the Tafazzin (TAZ)-EGFR signaling pathway, and has been shown to promote retinoblastoma proliferation." (PMID 33282720, 2020). "Analysis of tumour samples and cell lines derived from resistant EGFR mutant patients revealed that Retinoblastoma (RB) is lost in 100% of these SCLC transformed cases, but rarely in those that remain NSCLC." (PMID 25758528, 2015). "A study using a retinoblastoma cell line showed that the MAPK pathway activates Cav3.1 expression, which can be inhibited by epidermal growth factor receptor (EGFR) or ERK inhibitors." (PMID 39596484, 2024). "Moreover, TBMS II can reduce the redox related oxidative stress, inhibit the activation of epidermal growth factor receptor (EGFR) and inhibit TGF-β1-induced multiple transfer steps, thereby inhibiting the adhesion, migration of human retinoblastoma cells and invasion." (PMID 36160391, 2022).
Salmonella Infections (11 papers, 2010 to 2025). Infections with bacteria of the genus SALMONELLA. "Importantly, inhibition of EGFR and HIF1α restored both proteomics and metabolomics changes caused by Salmonella infection." (PMID 33868285, 2021). "Consistently, Gefitinib treatment of S. Typhimurium-infected mice showed recovery associated with inhibition of HIF-1α, further emphasizing the critical role EGFR-HIF-1α axis regulating Salmonella infection in vivo." (PMID 33868285, 2021). "Our in vitro data indicated that EGFR pathway is crucial for the establishment of Salmonella infection." (PMID 33868285, 2021). "A previous study of ours revealed that Salmonella infection mediated by Rck required an interaction with EGFR on the host cell surface, leading to internalization of the bacteria." (PMID 33330131, 2020). "To understand the role of EGFR-mTOR-HIF-1α pathway in Salmonella infection, we treated the infected cells with respective inhibitors like Gefitinib, Rapamycin, and Acriflavin to check whether Salmonella survival within the macrophages is affected." (PMID 33868285, 2021). "Moreover, inhibition of EGFR signaling induces proteo-metabolomics reprogramming that mitigates the effects of Salmonella infection." (PMID 33868285, 2021). "Hence, our microarray data confirms previous research and extends the down-stream signaling of EGFR response to Salmonella infection and provides more comprehensive information about the EGFR pathway involved in Salmonella infection." (PMID 21172007, 2010). "One of the downstream signaling of EGFR involves mTOR and HIF-1α axis, which was also found to be significantly affected by Salmonella infection in THP-1 cells." (PMID 33868285, 2021). "To understand the immunological response mediated by EGFR and HIF-1α during Salmonella infection, we infected the mice with S. Typhimurium and treated them with Gefitinib or Acriflavin." (PMID 33868285, 2021). "Taken together, we report that blocking of the EGFR-HIF1α axis may act as a potent HDT, which may have translational potential in targeting drug-resistant Salmonella infection." (PMID 33868285, 2021).
tongue squamous cell carcinoma (11 papers, 2012 to 2025). A squamous cell carcinoma that arises from the tongue. "Gefitinib, a selective tyrosine kinase inhibitor of EGFR, induced a reduction in OCT4 and SOX2 levels in CAL‐27 and SCC‐15 cells, two human tongue squamous cell carcinoma cell lines." (PMID 31823521, 2020). "Inhibiting EGFR signaling decreases the proliferation, invasion, and tumor sphere‐forming capacity of CAL‐27 cells, a human tongue squamous cell carcinoma cell line." (PMID 31823521, 2020). "However, cetuximab, a monoclonal antibody that blockades the epidermal growth factor receptor (EGFR), is the only kinase-targeted drug available for treating tongue squamous cell carcinoma (TSCC)." (PMID 34283052, 2021). "The resulting protein expression levels of EGFR and SQSTM1 in tumor tissue of all OSCC patients including buccal mucosa squamous cell carcinoma (BMSCC) and tongue squamous cell carcinoma (TSCC) patients were significantly higher than those in the CTAN tissues (all p < 0.001)." (PMID 34830108, 2021). "Of relevance to this study, Jiang and co-workers reported IGF1R expression, but not EGFR expression, being inhibited by miR-7 in tongue squamous cell carcinoma cells." (PMID 23115635, 2012).